PDLIM1 (PDZ and LIM domain 1)
Diseases named in the same sentence as PDLIM1 in open-access papers (continued):
Sharing a sentence is not in itself a finding about the gene and the disease.
pancreatic adenocarcinoma (2 papers, 2021 to 2023). "In addition, PDLIM1 also acts as a tumor antigen to induce antibody responses in pancreatic adenocarcinoma (PAAD), but whether this immune response is tumor-specific needs further investigation." (PMID 37894409, 2023).
pancreatic cancer (2 papers, 2021). "However, the role of PDLIM1 in pancreatic cancer still needs further research, which may help to explore the potential of PDLIM1 as an early diagnostic marker or drug target for pancreatic cancer." (PMID 34396044, 2021). "The pancreas/ampullary adenocarcinoma tissue array further proved the immunoreactivity of PDLIM1 against pancreatic cancer." (PMID 34396044, 2021).
sarcoma (2 papers, 2022 to 2024). A usually aggressive malignant neoplasm of the soft tissue or bone. "In sarcoma, PDLIM1 regulates the Hippo pathway by inhibiting E3 ligase AIP-4, which mediates YAP1 degradation." (PMID 39548074, 2024).
aneurysm (1 paper, 2025). Bulging or ballooning in an area of an artery secondary to arterial wall weakening. "Immunohistochemistry and WB confirmed reduced PDLIM1 expression in the aneurysm model and sh-PDLIM1 groups compared to controls, with oe-PDLIM1 restoring expression." (PMID 40881324, 2025). "This study reveals that PRDM9 regulates ACTN2 expression through epigenetic modifications and interacts with PDLIM1 to mediate VSMC function and aneurysm progression." (PMID 40881324, 2025).
Ataxia (1 paper, 2020). Ataxia refers to impaired coordination of voluntary muscle movement. "Other genes are related to cytoskeleton remodeling, including Cdh4, Pcdh9, Dock5, Dock3 for the proprioceptors (mutation of Dock3 is known to results in ataxia) and Stom and Pdlim1 for mechanoreceptors, as well as ion channels (Asic1 and Kcnip2 for proprioceptive fate)." (PMID 32826903, 2020).
bladder cancer (1 paper, 2024). "Most disulfidoptosis genes were downregulated in multiple cancer types, including PDLIM1, TLN1, and MYH10 in lung squamous cell carcinoma (LUSC), MYL6 and DSTN in prostate adenocarcinoma (PRAD), and FLNA and ACTB in bladder cancer (BLCA)." (PMID 38862242, 2024).
cerebrovascular disease (1 paper, 2022). "Nevertheless, there is little information available regarding the role of PDLIM1 in cardiovascular or cerebrovascular disease." (PMID 34978375, 2022).
diffuse large B-cell lymphoma (1 paper, 2024). "This study aimed to investigate PDLIM1 expression pattern and its functional role in diffuse large B-cell lymphoma (DLBCL) both in vitro and in vivo." (PMID 39564935, 2024).
dyslipidemia (1 paper, 2022). "A distinctive expression profile of PDLIM1 which is critically involved in NF-κB-mediated inflammation has been observed in the blood of patients with several chronic diseases including cardiovascular disease, hypertension, dyslipidemia and T2DM43." (PMID 36175575, 2022).
Friedreich ataxia (1 paper, 2016). An inherited condition that affects the nervous system and causes movement problems. "We suggest that in addition to frataxin expression, blood lymphoblast levels of NCF2 and PDLIM1 could be useful biomarkers for disease progression and drug effect in future clinical trials of Friedreich’s ataxia." (PMID 27078885, 2016).
hyperlipidemia (1 paper, 2022). "Analysis of upregulated DEGs has shown that the following seven genes were common between all complications of TIDM (hyperlipidemia, neuropathy, ketoacidosis, hypothyroidism and PCOS): SPINK9, TRDN, PVRL4, MYO3A, PDLIM1, KIAA1614 and GRP." (PMID 36175575, 2022).
idiopathic pulmonary hypertension (1 paper, 2024). "Furthermore, the results indicated an increase in the expression of DEGs related to the reactive oxygen species pathway (NDUFB4, PDLIM1, GPX4, and JUNB), and a decrease in the expression of SOD, which has an antioxidant function, in the presence of idiopathic pulmonary hypertension." (PMID 38586587, 2024).
non-small cell lung carcinoma (1 paper, 2020). A group of at least three distinct histological types of lung cancer, including non-small cell squamous cell carcinoma, adenocarcinoma, and large cell carcinoma. "A prognostic risk index, grounded on four persister genes (LYNX1, SYNPO, GADD45B, and PDLIM1), was constructed in non-small-cell lung cancer patients from The Cancer Genome Atlas Program (TCGA) using stepwise Cox regression analysis." (PMID 33330109, 2020).
ovarian mucinous adenocarcinoma (1 paper, 2021). An invasive adenocarcinoma that arises from the ovary and is characterized by the presence of malignant epithelial cells that contain intracytoplasmic mucin. "Although the positive rate of anti-PDLIM1 AAb in ovarian mucinous adenocarcinoma was as high as 75% (3/4), the sample size was too small to make a difference (p>0.05, Fisher’s exact test)." (PMID 34489945, 2021).
systemic lupus erythematosus (1 paper, 2024). An autoimmune multi-organ disease typically associated with vasculopathy and autoantibody production. "Meanwhile, KEGG results indicated that genes positively associated with PDLIM1 were involved in systemic lupus erythematosus in Homo sapiens, suggesting a role in inflammatory responses." (PMID 39200304, 2024).
thrombosis (1 paper, 2016). "However, studies have also suggested a role in platelets, and recent work on Pdlim1 (CLP36) revealed that loss-of-function of the protein in mice results in arterial thrombosis." (PMID 27792740, 2016).
type 2 diabetes (1 paper, 2023). "In comparison, in the type 2 diabetes model we studied, it was found that the expression of PDLIM1 was down-regulated, and the invasion and migration of cells were enhanced after PDLIM1 decreased." (PMID 37037887, 2023).
cancer (26 papers, 2017 to 2025). A tumor composed of atypical neoplastic, often pleomorphic cells that invade other tissues. "PDLIM1-deficient mice demonstrate increased levels NF-κB-mediated inflammation, which results in elevated production of pro-inflammatory cytokines and chemokines, which have been associated with cancer progression." (PMID 40278994, 2025). "The PDLIM1 gene encodes a protein involved in actin cytoskeleton organization and in regulating signaling pathways, including the NF-κB pathway, which plays a critical role among others in inflammation, cancer cell proliferation, epithelial‐to‐mesenchymal transition, angiogenesis, and metastasis." (PMID 40278994, 2025). "CLP36 (PDLIM1) is an actin-associated scaffold as a target hit and localizes to a variety of actin cytoskeletal elements, which is diffusely expressed in gastrointestinal tract, muscle, heart tissues and serves a cell-cell adhesion and focal adhesion modulator with functional importance in cancer." (PMID 39735560, 2024). "As a crucial player in cytoskeletal organization and organ development, CLP36/PDLIM1 has been recently demonstrated to be dysregulated in a variety of cancers with important roles in the proliferation and metastasis during tumor initiation and progression." (PMID 39735560, 2024). "The loss of this tumor-suppressor miRNA within DLBCL cell lines can lead to the upregulation of oncogenes, such as PDLIM1, which in turn promotes cancer development." (PMID 39564935, 2024). "A large body of evidence indicates that PDLIM1 is dysregulated in various types of cancers, contributing to tumor development and growth." (PMID 38739940, 2024). "Overall, the evidence indicates that PDLIM1 possesses distinct tissue-specific effects in different cancer types, likely by regulating different signaling pathways and targets." (PMID 38739940, 2024). "Among the specifically expressed genes of each subgroup, PDLIM1 correlated only with three other cancer stem cell markers, namely PDGFRA, RBP1, and ITM2A." (PMID 39548074, 2024). "From this perspective, PDLIM1 is a promising target for the treatment of various cancers, including its deep relationship with the molecular mechanisms and disulfidptosis." (PMID 38739940, 2024). "Nevertheless, in other types of cancers (e.g., breast cancer and chronic myelogenous leukemia), PDLIM1 can promote cancer progression." (PMID 38739940, 2024). "By re-analyzing scRNA-seq data, we found that among these genes, only PDLIM1 was specifically expressed in the cancer stem cells, although the other six genes showed some enrichment in cancer stem cells." (PMID 39548074, 2024). "The results showed significantly increased PDLIM1 expression in tumor samples compared to non-carcinoma samples." (PMID 39564935, 2024). "Consistent with the mRNA results, PDLIM1 protein levels were elevated in DLBCL samples relative to non-carcinoma samples." (PMID 39564935, 2024). "Recent studies have shown that the expression of PDLIM1 is aberrant in cancers, such as HCC9, CRC10 and CML16." (PMID 37414929, 2023). "Further, the dysregulation of PDLIM1 expression in cancers affects a series of signaling pathways, such as Hippo-YAP, Wnt/β-catenin and NF-κB signaling." (PMID 37414929, 2023). "To conclude, our research has unveiled a novel molecular mechanism for GC treatment: PDLIM1 mediates the Hippo-YAP signaling pathway to exert a cancer-suppressing function and strengthen the sensitivity of GC to cisplatin." (PMID 36164345, 2022). "In this review, we summarize the structure and function of PDLIM1 and outline the research progress of PDLIM1 in human cancers." (PMID 34396044, 2021). "In this review, we summarize the structure and function of PDLIM1, as well as its important roles in human cancers." (PMID 34396044, 2021). "Through interacting with actin filaments and other proteins, PDLIM1 can regulate the proliferation, metastasis and survival of malignant cells, and ultimately affect the progression of cancers." (PMID 34396044, 2021).
cancer (continued). "In cancer, however, the dysregulation of PDLIM1 can lead to abnormalities in a series of signaling pathways." (PMID 34396044, 2021). "The persister gene panel (LYNX1, SYNPO, GADD45B, and PDLIM1) was established and its role to elucidate radio-response and clinical outcome after radiotherapy was subsequently validated across several cancer types." (PMID 33330109, 2020). "Locus 10q24.1 also spans cancer-associated genes ENTPD1 and PDLIM1." (PMID 40278994, 2025). "Cancer stem cells were the only subgroup significantly correlated with PDLIM1 expression." (PMID 39548074, 2024). "Several studies suggest that PDLIM1 plays a suppressive role in cancer progression." (PMID 39548074, 2024). "Previous study showed that PDLIM1 acts differently in different cancers." (PMID 37414929, 2023). "A previous study reported that PDLIM1 could interact with and stabilize the E‐cadherin/β‐catenin complex in cancer." (PMID 34978375, 2022). "Thus, confirming the correlation between PDLIM1 and the regulation of the Hippo pathway seems to be of great significance in human cancers, particularly GC." (PMID 36164345, 2022). "It seems that PDLIM1 plays different regulatory roles in different kinds of cancer cells." (PMID 34489945, 2021). "However, other studies predominantly highlight PDLIM1’s promotive functions in cancer." (PMID 39548074, 2024). "Interestingly, PDLIM1 displays remarkable tissue-specific roles across cancers." (PMID 34396044, 2021). "Therefore, it seems reasonable to speculate that the tissue-specific characteristics of PDLIM1 may depend on the difference in its interacting proteins and regulatory signaling pathways in different cancer types." (PMID 34396044, 2021). "The dysregulation of PDLIM1 usually manifests as its abnormal expression, which affects the interaction with its binding proteins and the related signal pathways (such as NF-κB, Wnt/β-catenin and Hippo), leading to the occurrence and development of many diseases including cancer." (PMID 34396044, 2021). "Other cancer-related genes located at the same locus include ENTPD1 (Ectonucleoside triphosphate diphosphohydrolase-1), and PDLIM1 (PDZ And LIM Domain 1)." (PMID 40278994, 2025). "PDZ And LIM domain protein 1 (PDLIM1), a protein-coding gene, has been widely reported to exhibit differential expression patterns across various human cancers, including hematological malignancies." (PMID 39564935, 2024). "DSTN and FLNB were downregulated when ACTIN4, INF2, MHY10, FLNA, PDLIM1, and IQGAP1 were upregulated in THCA cancer tissues." (PMID 38584831, 2024). "The interaction between PDLIM1 and miR-3940-5p and its effects on DLBCL cellular activities and cancer development were further explored using a DLBCL mouse model." (PMID 39564935, 2024). "We obtained 76 DLBCL and 76 matched non-carcinoma clinical samples from DLBCL cases., and the PDLIM1 levels were quantified using real-time quantitative PCR (qRT-PCR)." (PMID 39564935, 2024). "The Hippo pathway has a huge function in different cancers, but its correlation with PDLIM1 has not been elucidated." (PMID 36164345, 2022). "Moreover, ALX4, PDLIM1, CAP2 and EDIL3 have also been found to be correlated with the prognosis of cancer." (PMID 28178989, 2017).
tumor (23 papers, 2016 to 2025). "PDLIM1 was specifically expressed in GSCs and was associated with poor prognosis and advanced tumor stages." (PMID 39548074, 2024). "Tumoroids demonstrated upregulation of oncogene-associated genes (Ackr3, Adcy3, Fam222) and downregulation of tumor suppressor genes (Casz1, Frk, Homer2, Pdlim1)." (PMID 40772227, 2025). "Compared to the WT group, PDLIM1-OE led to more advanced tumor growth, as shown by the tumor weight and volume." (PMID 39548074, 2024). "Studies have revealed diverse functions of PDLIM1 across various tumor tissues, wherein it can either impede epithelial-mesenchymal transition (EMT) and tumor cell infiltration and metastasis or promote tumor development." (PMID 38836761, 2024). "PDLIM1 is a tumour-suppressing gene that effectively blocks the Hippo-Yes-associated protein (YAP) signalling pathway." (PMID 39061076, 2024). "The correlation analysis demonstrated that PDLIM1 expression correlated with B symptoms, tumor Ann Arbor stage, and international prognostic index score." (PMID 39564935, 2024). "To further investigate the role of PDLIM1-OE in vivo, we performed xenograft tumor assays in SCID nude mice." (PMID 39548074, 2024). "Meanwhile, we also performed soft agar assays and found that both the tumor sphere counts and diameters were significantly increased with PDLIM1-OE for both U87 and A172 cells." (PMID 39548074, 2024). "Patients were then stratified into high- and low-expression groups (high or low; n = 38 per group) based on the median expression value of PDLIM1 in the tumor samples determined by qRT-PCR." (PMID 39564935, 2024). "Western blot analysis confirmed reduced PDLIM1 expression in tumor samples from the PDLIM1 knockdown group." (PMID 39564935, 2024). "In the mouse model of DLBCL, PDLIM1 knockdown reduced tumor volume and weight, further supporting the notion that PDLIM1 knockdown can effectively suppress tumor growth." (PMID 39564935, 2024). "Previous studies have suggested that PDLIM1 is crucial in various physiological conditions and cell proliferation and metastasis during tumor progression." (PMID 37037887, 2023). "Emerging evidence demonstrates that PDLIM1 is dysregualted in a variety of tumors and plays essential roles in tumor initiation and progression." (PMID 34396044, 2021). "Moreover, we performed immunohistochemistry staining against PDLIM1 on the GBM section slides along with the para-tumor normal brain tissue slides." (PMID 39548074, 2024). "PDLIM1 silencing significantly suppressed tumor growth compared to the control group." (PMID 39564935, 2024). "PDLIM1 could inhibit tumor metastasis and EMT by interacting with E-cadherin/β-catenin adhesion complex, inhibiting the Hippo signaling pathway." (PMID 38694875, 2024). "Furthermore, PDLIM1 silencing not only reduces tumor growth but also promotes apoptosis in DLBCL tumors, highlighting its potential as a therapeutic target." (PMID 39564935, 2024). "Notably, mice bearing PDLIM1-knockdown tumors exhibited decreased average tumor size compared to controls, providing strong evidence for the inhibitory effect of PDLIM1 suppression on DLBCL cell proliferation." (PMID 39564935, 2024). "In some tumor diseases, PDLIM1 has been reported to play a key role in regulating the Wnt pathway." (PMID 37037887, 2023). "Moreover, PDLIM1 plays important roles in cell proliferation and metastasis during tumor initiation and progression." (PMID 34396044, 2021). "Therefore, PDLIM1 may serve potentially as a marker of tumor aggressiveness and as a predictor of survival in CRC patients." (PMID 34396044, 2021). "By immunohistochemistry against Ki67 on the tumor slides of both the WT and PDLIM-OE groups, we noticed a significant upregulation of Ki67 in the PDLIM1-OE group, which was consistent with the results in vitro." (PMID 39548074, 2024). "PDLIM1 and ACTN4 were mainly expressed in endothelial cells, fibroblasts, smooth muscle cells, and tumor/epithelial cells." (PMID 38694875, 2024).
tumor (continued). "In view of the role in promoting proliferation and suppressing apoptosis, PDLIM1 was found to be an oncogene in CML, and the overexpression of PDLIM1 weakened the tumor suppressive role of miR-370-3p in CML, indicating that miR-370-3p functions partially depends on the repression of PDLIM1." (PMID 34396044, 2021). "In colorectal cancer, the absence of PDLIM1 promotes the expression of epithelial-mesenchymal transition (EMT) markers and enhances the invasive and migratory characteristics of tumor cells." (PMID 38739940, 2024).
breast (2 papers, 2017 to 2020). "PDLIM1 overexpression attenuated the epithelial-mesenchymal transition of colorectal cancer cells." (PMID 33033380, 2020).
PDLIM1 also shares sentences with these, for which no sentence is quoted: glioblastoma (4 papers); cardiac hypertrophy (2); cardiovascular disease (2); esophageal squamous cell carcinoma (2); acute myeloid leukemia (1); cardiomyopathy (1); cognitive disorder (1); colon adenocarcinoma (1); cystinuria (1); fibrosarcoma (1); hematological malignancies (1); Hypertension (1); hypothyroidism (1); infection (1); intracranial aneurysms (1); liver cancer (1); liver disease (1); lung adenocarcinoma (1); lung squamous cell carcinoma (1); lymph node metastasis (1); neurodegenerative disease (1); neuropathy (1); orofacial cleft (1); ovarian benign tumors (1); Pneumocystis infection (1); prostate adenocarcinoma (1); renal fibrosis (1); thymic lymphoma (1); type 1 diabetes mellitus (1).